EGFR (epidermal growth factor receptor)
Diseases named in the same sentence as EGFR in open-access papers (continued):
Sharing a sentence is not in itself a finding about the gene and the disease.
tumor (continued). "Furthermore, in the tumours with high EGFR expression, a clear reduction in tumour ratio was seen in the AT13387 treatment group." (PMID 26627081, 2016). "The tumor cells have the mutant genome and they express the mutant EGFR mRNA." (PMID 27352172, 2016). "Ten patient samples were evaluated for EGFR mutations; however, direct sequencing analysis revealed no mutations in any of the tumor samples, likely due to the low mutation rate reported in ESCC." (PMID 28087951, 2016). "To further identify the clinical importance of VEGF/EGFR in CRC, we analyzed the correlationship between the VEGF/EGFR protein level with clinicopathological characteristics, including age, gender, tumor size, histology, tumor location, differentiation status, hepatic metastasis and TNM stage." (PMID 27729020, 2016). "Such hetero-complex formation and activation of RET may operate in MLS cells as EGFR is strongly expressed in the tumor cells." (PMID 26595521, 2016). "Thus, both the EGFRL858R mice treated with erlotinib and the EGFRL858R/T790M mice treated with afatinib-cetuximab, the dramatic tumor response was accompanied by reduced downstream EGFR signaling." (PMID 27494838, 2016). "However, recent reports demonstrated that affinity of single-chain variable fragment (scFv) of CAR can be tuned to distinguish tumor cells from normal cells based on the disparate density of EGFR expression." (PMID 27833557, 2016). "Additionally, the EGFR expression can serve as an independent marker indicative of tumor invasion and metastasis Radiotherapy was found to be a confounder of the distribution of EGFR express, and this result should be verified by future studies." (PMID 27399694, 2016). "Only patients with a KRAS wild-type tumor may benefit from additional (third-line) treatment with an epidermal growth factor receptor (EGFR)-targeted monoclonal antibody (panitumumab or cetuximab)." (PMID 27782851, 2016). "If we were to use only an IGF1R receptor inhibitor, the cancer cells expressing EGFR or insulin receptors would not be eliminated, thus eventually causing tumor recurrence." (PMID 27460078, 2016). "Additionally, EGFR-mediated signaling pathways confer growth and survival advantages to tumor cells, promoting a state of continuous and unregulated proliferation." (PMID 27437777, 2016). "For the 41 patients with paired samples obtained after acquisition of EGFR-TKI resistance, the concordance for mutation detection by ddPCR in plasma compared with tumor tissue or malignant fluid specimens was 78.0% for TKI-sensitizing mutations and 65.9% for T790M." (PMID 27542267, 2016). "Likewise, EGFRL858R staining also decreased significantly, confirming that the transgenic mutant EGFR-expressing tumor cells were depleted within 24 hours of erlotinib treatment." (PMID 27494838, 2016). "For example, our findings that concurrent treatment with crizotinib can re-sensitize EGFR-mutant tumours with MET amplification to rociletinib suggest that personalized targeting of multiple resistance mechanisms may be of significant clinical utility." (PMID 27283993, 2016). "In our previous study, clinically applied JX-594 conferred tumor selectivity via viral thymidine kinase (vTK) inactivation because vaccinia virus has evolved to replicate in EGFR pathway-activated cells, which are usually cancer cells with high cellular TK levels." (PMID 26918725, 2016). "One of the EFEMP1 variants was identified as the sought-after ETSP, which had a stronger tumor-suppression function in TMCs by targeting EGFR and angiogenesis, and a new tumor-suppression function in STICs by targeting NOTCH signaling and MMP2-mediated cell invasion." (PMID 27713911, 2016). "Moreover, the nanoparticles suppressed the EGFR–ERK–NF-κB signaling pathways as well as the expression of the related tumor promoting proteins MMP-9 and XIAP, and subsequently inhibited the migration and invasion capabilities of cancer cells." (PMID 27833124, 2016).
tumor (continued). "Thus our data suggested that overexpression of wt-EGFR is tumorigenic and sensitizing tumor cells to TKI." (PMID 26646697, 2016). "EGFR is commonly highly expressed in a variety of malignant tumors, and the abnormal activation of EGFR is closely correlated with tumor cell biology, acting as an indicator of poor prognosis for the patients with cancer." (PMID 28119606, 2016). "EGFR is a member of the ErbB family, tyrosine kinase receptors with growth promoting effects which play a significant role in signaling pathways including cell proliferation, angiogenesis, and tumor progression." (PMID 26881213, 2016). "Interestingly, introduction of an MEK inhibitor in combination with cetuximab resensitised the tumour to anti-EGFR therapy." (PMID 27340376, 2016). "Lower tumor response rates have been observed in never smokers and patients with EGFR mutations or ALK rearrangements when compared to heavy smokers." (PMID 27234522, 2016). "An heterogeneous tissue staining of HIF-1α,HIF-2α, and EGFR has been observed in this tumor." (PMID 27303300, 2016). "The association between BM and mutation in PIK3CA and BRAF, expression of NCAM, EGFR, and CXCR4, MGMT methylation and increase in the tumor marker CA19.9 have also been investigated, but only in one or two studies each and on small samples, so the possible predictive potential is hard to determine." (PMID 27037031, 2016). "The quest to find tumours dominated by a unique molecular alteration that could be targeted as effectively as in the case of EGFR and ALK mutants is a fast evolving field." (PMID 27350784, 2016). "Importantly, the reduction in tumor growth was more obvious in mice treated with EGFR-CAR NK-92 combined with oHSV-1 than in those treated with EGFR-CAR NK-92 alone or oHSV-1 alone." (PMID 27050072, 2016). "Since exosomes are involved in cell- cell communication that alters the phenotype of the recipient/target cells, exosomal-EGFR expressed by various tumor types, including PCa may play an important role in cancer progression." (PMID 27152724, 2016). "This signal attenuation is partially due to erlotinib inhibition of EGFR pathways in tumor cells." (PMID 27494838, 2016). "The deletion of NFKBIA (encoding nuclear factor of κ-light polypeptide gene enhancer in B-cells inhibitor-α), an inhibitor of the EGFR-signaling pathway, is reported to promote tumor development in GBM, which does not show mutations of EGFR." (PMID 27338365, 2016). "In I-type adenocarcinomas, high EGFR expression was significantly associated with larger tumour size, but not with any other parameter." (PMID 27070783, 2016). "Thus, taken together, our findings suggested that TGF-β and hypoxia/reoxygenation promoted tumor progression and radioresistance of A549 cells through ROS-mediated activation of Nrf2 and EGFR." (PMID 26904167, 2016). "Two possibilities could potentially explain drug sensitivity in these patients: 1) wt-EGFR overexpression is tumorigenic and thus sensitizes tumor cells to TKIs; or 2) tumors are driven by other kinases that can be coincidently inhibited by gefitinib." (PMID 26646697, 2016). "It has been reported that NRP1 can control EGFR signaling and tumor growth." (PMID 27881077, 2016). "Thus, as with earlier generations of EGFR TKIs, a significant fraction of patients develop multiple resistance mechanisms to rociletinib, reflecting the clinical importance of tumour heterogeneity." (PMID 27283993, 2016).
tumor (continued). "Re-biopsy of the AZD9291 resistant tumor identified an EGFR activating mutation and CMET amplification without T790M or C797S mutation." (PMID 27448564, 2016). "Few authors claim that the sEGFR could be a traditional “positive biomarker” released in biological fluids by tumor cells that normally express high levels of the EGFR." (PMID 27104520, 2016). "These ELM4-ALK positive tumours, like those with mutations in EGFR, either show a lack of response to ALK-specific TKIs such as crizotinib (Xalkori) or relapse with drug resistant disease." (PMID 26791049, 2016). "Moreover, studies on non-small cell lung cancer (NSCLC) and CRC cell lines have shown that tumour cells that have undergone EMT are much less sensitive to anti-EGFR treatment." (PMID 27160084, 2016). "sEGFR might therefore also influence kinetics and tumor uptake of tracer doses used for 89Zr-labeled EGFR targeting antibodies." (PMID 27602494, 2016). "In addition, anlotinib showed antitumor activity against tumor cells carrying mutations in PDGFR α, c-Kit, Met, and epidermal growth factor receptor (EGFR)." (PMID 27716285, 2016). "One controversial result was reported 0.35 μM of gefitinib failed to inhibit tumor growth in patients who are mutation-positive in a previous study that investigated the correlation of EGFR mutation and drug sensitivity using the CD-DST." (PMID 27070423, 2016). "Furthermore, overexpression of Dsg2 in the epidermis of transgenic mice enhances EGFR level and activates mitogenic signaling leading to epidermal hyperplasia and sensitivity to tumor development." (PMID 26918609, 2016). "Notably, mutation of PTEN at residue 138 occurs in several tumor and inactivates PTEN with loss of the control of Rab7-dependent endosomal degradation of EGFR and consequent uninterrupted growth signaling with important implications for tumor progression." (PMID 27548222, 2016). "Decisions on first-line treatments are based on the target oncogenes identified in tumor tissues; thus, the tumors of patients with NSCLC should be tested for EGFR mutations to determine whether an EGFR-TKI is the appropriate first-line therapy." (PMID 27519791, 2016). "Cannabidiol inhibits the EGF/EGFR pathway and alters cytokine production in tumor cells, leading to a reduction in the numbers of total and M2 macrophages at the primary and secondary tumor sites." (PMID 27683110, 2016). "All 220 tumour samples were analysed with EGFR and HER2 IHC." (PMID 27387915, 2016). "Thus further investigation is needed to evaluate EGFR inhibitors for modulating T cell mediated tumor killing in antigen specific manner." (PMID 27467256, 2016). "No EGFR kinase domain mutations were detected in any of the tumours from 36 patients evaluable for EGFR tumour mutation status." (PMID 26766738, 2016). "Indeed, a recent preclinical study with patient derived xenografts indicated that strongest response to anti-EGFR therapy was achieved in tumours with EGFR gene amplification." (PMID 27387915, 2016). "As EGFR acts through the PIK3CA/AKT pathway, mutations in that pathway might be anticipated to provide a resistance mechanism for the tumor cells." (PMID 27304188, 2016). "COX-2 overregulation and the resulting increase in PGE2 levels induced overexpression of EGFR pathways and may represent a strategy adopted by tumors that contributes to the evasion of tumor-specific immune response." (PMID 28053982, 2016). "In addition, recent studies suggest the critical roles of EGFR-mediated signaling in regulation of expression of an immune checkpoint molecule, programmed death-ligand 1 (PD-L1) in tumor cells." (PMID 27833557, 2016).
tumor (continued). "In a separate experiment we examined the effects of these Abs on the growth of tumor cells expressing EGFR In Vitro and In Vivo, that is, in athymic mice and reported that the results are very heterogeneous among the Abs that included already approved therapeutic Abs, Erbitux and Vectibix." (PMID 27834817, 2016). "Current strategies to deliver an effective and persistent dose of anti-EGFR monoclonals to the GBM tumor microenvironment have not been successful, in part because the blood brain barrier severely limits the systemically administered anti-EGFR therapy from accessing the tumor microenvironment." (PMID 27711187, 2016). "The tumor was negative for epidermal growth factor receptor mutation but positive for the EML4-ALK fusion oncogene according to fluorescence in situ hybridization." (PMID 26964537, 2016). "After crosslinking with the GE11 polypeptide, VLPs could target EGFR-positive cells, especially tumor cells, which greatly reduce the possibility of side effects." (PMID 26992211, 2016). "EGFR T790M mutations were also examined with specificity of 63%, possibly related to tumor heterogeneity and false-negative tissue genotyping." (PMID 27588476, 2016). "To ascertain whether high EGFR expression was related to EGFR gene amplification, we assessed amplification status in a subset (18 cases) of tumours that showed the highest expression using H score), which included 16 BOTs and 2 LGSCs." (PMID 26870997, 2016). "Therefore, the imaging responses predict early anti-tumor efficacy of EGFR-targeted treatment of EGFR-addicted tumors." (PMID 27494838, 2016). "Several randomized studies demonstrated that, for EGFR mutated NSCLC, first-line TKI therapy could provide higher tumor response rates (RR) and longer progression-free survival (PFS) than chemotherapy." (PMID 27637087, 2016). "It has been suggested that EGFR status in vivo might be studied in serial biopsies of normal and tumor tissues." (PMID 27388754, 2016). "In both the PRIME and OPUS studies, a negative effect on efficacy was reported from combining an EGFR mAb with FOLFOX4 among patients whose tumours harboured a RAS mutation." (PMID 26766738, 2016). "To explore the molecular mechanism through which miR-218-5p contributes to cancer suppression, we provided evidence that the targeting of EGFR may be the pathway by which miR-218-5p exerts its tumor-suppressing function." (PMID 27057632, 2016). "Decision management could be guided by knowledge of the residual EGFR TKI sensitivity of the tumor lesions." (PMID 26857779, 2016). "Immunomodulatory effects could be a third mechanism by which ginsenoside Rg3 enhanced the anti-tumor effects of EGFR-TKI." (PMID 27655708, 2016). "In summary, N19 may act as a novel dual inhibitor of EGFR and cMET that induces apoptosis in TKI-resistant EGFR-mutated NSCLC cells and suppresses xenograft tumor formation." (PMID 27362807, 2016). "The multiple level of interactions that exist in EGF signaling, RAS, and cell survival, proliferation and invasion, indicated that high plasma TIMP-1 levels may interact with EGFR signaling and thereby affect the anti-tumor effects of EGFR inhibitors." (PMID 27509063, 2016). "miR‐133a‐MB delivery using ultrasound led to tumor regression by knockdown of EGFR." (PMID 27465833, 2016). "Therefore, activated PBNK cells were combined with cetuximab or panitumumab to test their ADCC efficacy on EGFR+/-, RASwt/mut, BRAFmut cell lines and primary tumor cells from patients with CRC." (PMID 27314237, 2016). "The important lesson we have learned from clinical trials and drug resistance experiments is that the combination between the unique biochemical characteristics of each EGFR inhibitor and the genetic heterogeneity of a tumour is the major determinant of response." (PMID 27350784, 2016). "Comparison of EGFR and SHP2 IHC scores in each tumor showed a tight association in expression." (PMID 26728598, 2016).
tumor (continued). "Molecular-targeted therapy with cetuximab, an anti-epidermal growth factor receptor-specific chimeric monoclonal antibody, has been also demonstrated to inhibit tumor growth, cancer cell invasion, angiogenesis, and metastasis, thereby improving overall survival in head and neck OSCC patients." (PMID 27050375, 2016). "However, this monoclonal antibody is able to eliminate EGFR-expressing tumor cells via ADCC at much lower concentrations, suggesting ADCC as an important antitumor mechanism of cetuximab." (PMID 26824186, 2016). "Blocking either IL-17E or its receptor in combination with EGFR inhibitor administration might reduce the likelihood of tumor resistance and enhance therapeutic efficacy." (PMID 27462789, 2016). "Thus, the mechanism determining how the HLA-DPB1 variation affects the risk of EGFR mutation-positive LADC should be further investigated, particularly with respect to the possibility that it affects immune responses against EGFR-positive tumour cells." (PMID 27501781, 2016). "Wt-EGFR overexpressing 3T3 cells is capable of forming tumor nodules in nude mice." (PMID 26646697, 2016). "Bertotti et al35 recently carried out exome sequence and copy number analyses of both patient‐derived xenografts and patient tumours, to investigate the effects of mutations in ERBB2, EGFR, FGFR1, PDGFRA and MAP2K1 in relation to resistance to anti‐EGFR therapies." (PMID 26690310, 2016). "Furthermore, EGFR(2R)-lytic hybrid peptide markedly suppressed the tumour growth of OSCC cells in a xenograft model." (PMID 26956916, 2016). "This implies that TKI suppression of EGFR signaling might result in a feedback activation of Stat3 signaling and thus its tumor-promoting activity as well." (PMID 27419630, 2016). "In addition, they showed that this dietary pattern can down-regulate tumor suppressor miRNA-143 and miRNA-145 through EGFR signaling, which further up-regulated their target oncogenes, MYC and KRAS, resulting in increased tumorigenesis." (PMID 27681738, 2016). "Importantly, however, these studies included no patient selection based on the histological subtype of the tumours, EGFR protein expression or EGFR gene copy number (GCN) analysis." (PMID 27387915, 2016). "The same EGFR status in the MP and solid portions of a tumour mass suggested that they may have the same origin and response to EGFR-TKI." (PMID 27046167, 2016). "Importantly while free MMAE radiosensitized indiscriminately, antibody conjugation resulted in targeted MMAE radiosensitization to EGFR or HER2 expressing tumours." (PMID 27698471, 2016). "Therefore, more precise and detailed studies are warranted to clarify relationship between mutant EGFR status and PD-L1 expression in tumor tissues." (PMID 27833557, 2016). "ZEGFR:2377 binds to membranous EGFR and is barely internalized in A431 during at least 5 hrs, although the degree of internalization may vary depending on the tumor and time." (PMID 27388754, 2016). "We have previously shown that WM130 could inhibit the growth of tumor xenografts and suppress EGFR and PTEN/AKT signaling pathways." (PMID 27783993, 2016). "Thus, first of all we investigated the endogenous expression of this protein in a panel of five human tumor cell lines differently expressing EGFR." (PMID 27732953, 2016). "This might be because c-Met-activated tumor cells could presumably proliferate despite EGFR-TKI therapy, and initial disease control was followed by a relatively short PFS compared with tumors without c-Met activation." (PMID 27213587, 2016). "This small trial of five patients with del E746-A750 and five patients with WT EGFR showed that the volume of distribution of the radiotracer was on average two times greater in the del E746-A750 EGFR than in the wild-type EGFR expressing tumours." (PMID 27552105, 2016).